HFE (homeostatic iron regulator)
Diseases named in the same sentence as HFE in open-access papers (continued):
Sharing a sentence is not in itself a finding about the gene and the disease.
tuberculosis (1 paper, 2011). A chronic, recurrent infection caused by the bacterium Mycobacterium tuberculosis. "Evidence suggests that individuals heterozygous for the C282Y mutation in the HFE gene may experience benefit due to more efficient dietary iron absorption and via increased resistance to typhoid fever and tuberculosis, diseases that became more prevalent with the rise of urbanization." (PMID 22151998, 2011).
cancer (26 papers, 2005 to 2026). A tumor composed of atypical neoplastic, often pleomorphic cells that invade other tissues. "The H63D variant of the HFE gene is reportedly a disease modifier for a number of neurodegenerative diseases and possibly cancer." (PMID 29391061, 2018). "To date, no study has established a selective mutation from wild‐type to HFEC282Y or HFEH63D within tumors that would enhance cancer progression 112 and there are contrasting reports on HFE mutations and cancer risk." (PMID 28474781, 2017). "The implications of HFE mutations in cancer development and progression have been extensively investigated since iron is essential for cell proliferation and is in higher demand in cancer metabolism." (PMID 28474781, 2017). "Two major HFE polymorphisms, H63D and C282Y, have been associated with an increased risk of cancers." (PMID 28358914, 2017). "The molecular mechanism of how C282Y increases cancer risk also merits further study, to aid understanding of the role of HFE gene mutation in carcinogenesis." (PMID 26893171, 2016). "This is the most comprehensive study reported to date, evaluating the association between HFE genotype and overall cancer risk, with stratification based on territory." (PMID 26893171, 2016). "In this compound study, we performed a meta‐analysis of the association between mutations of the HFE gene and risk of cancer including 36 eligible case–control or cohort studies." (PMID 26893171, 2016). "One hundred and twenty‐nine studies were found concerning the association between HFE mutation and cancer risk." (PMID 26893171, 2016). "Although disruptions in the maintenance of iron and cholesterol metabolism have been implicated in several cancers, the association between variants in the HFE gene that is associated with cellular iron uptake and cholesterol metabolism has not been studied." (PMID 24533143, 2014). "It has been widely reported that mutations in the HFE gene correlate with increased cancer risk, and that HH patients have a 20- to 200-fold higher probability to develop liver cancer compared to control patients, culminating in deaths in 45% of all HCC patients." (PMID 33921027, 2021). "The contribution of iron overload in cancer development is well-documented in patients suffering from a genetic iron overload disorder (hereditary hemochromatosis, HH), caused by mutations within the HFE gene." (PMID 33921027, 2021). "However, the association between HFE variants and the development of cancer needs further clarification." (PMID 32214052, 2020). "The HFE gene contains genetic polymorphisms identified as risk factors or disease modifiers for several human diseases such as hereditary hemochromatosis, neurodegenerative diseases, liver disease, and cancers." (PMID 31856248, 2019). "Both HFE polymorphisms are associated with increased cellular iron uptake which may indicate an increased need for iron for cancer cell proliferation." (PMID 28358914, 2017). "The impact of HFE polymorphisms on patient survival in cancers has been reported in 4 studies." (PMID 28358914, 2017). "To investigate the association between mutation of HFE (the principal pathogenic gene in hereditary haemochromatosis) and risk of cancer, we conducted a meta‐analysis of all available case–control or cohort studies relating to two missense mutations, C282Y and H63D mutations." (PMID 26893171, 2016). "The effect of territory on the association between HFE mutation and cancer could be a factor in susceptibility." (PMID 26893171, 2016). "A number of these genes, including ACYP1, MFF, SLC44A1, and HFE, promote cancer development by regulating metabolic pathways." (PMID 40503897, 2025). "TERT and HFE, which also affect both cancers, were expressed at low levels across hepatic cell types." (PMID 40823170, 2025). "Some of these upregulated genes, including HTATIP2, PRG4, and HFE, were previously reported to be involved in cancer metastasis." (PMID 31718700, 2019).
cancer (continued). "Among the many iron metabolism genes, the HFE (homeostatic iron regulator) gene has been interrogated for its relationship to cancer." (PMID 31856248, 2019). "In conclusion, our data demonstrated that two common H63D and C282Y HFE polymorphisms and several SNVs in the intron of the HFE gene were increased in TCGA GBM; and, require further investigation into the role of cancer development and progression." (PMID 28358914, 2017). "To estimate the penetrance of the HFE mutations we have carried out a cross-sectional study of histologically confirmed cases of HCC and used cancer registry data that is reliant on an accurate clinical diagnosis." (PMID 15929796, 2005). "The effect of other single nucleotide variant (SNV) in the HFE gene on cancer development and progression has not been systematically studied." (PMID 28358914, 2017). "Previous studies demonstrate that β2-M and HFE play an important role in cancer progression." (PMID 23874600, 2013). "Moreover, association between both hepcidin regulatory genes (HFE and HJV) was found in all grades and stages of this disease, except stages IIIB and IV of cancer." (PMID 24078156, 2013). "On the other hand, higher expression of HRAS, NRAS, APC, HFE, MMP9, and a high enrichment of MAPK/RAS, NFKB, and TNF signaling pathways are all evident in HLE cells as often seen in cancer." (PMID 30176945, 2018). "However, the effect of other single nucleotide variation (SNV) in the HFE gene on the cancer development and progression has not been systematically studied." (PMID 28358914, 2017).
genetic disorder (14 papers, 2008 to 2025). "The predominant HH form is linked to mutations in the HFE gene and constitutes the most frequent genetic disorder in Caucasians." (PMID 30420953, 2018). "The HFE gene is also known for regulating iron absorption, which results in recessive genetic disorders, such as hereditary haemochromatosis also related to AD." (PMID 35002653, 2021). "Studies on genetic disorders of iron metabolism and of corresponding animal models have identified the hemochromatosis proteins (HFE, TFR2 and HJV) as the iron-dependent regulators of hepcidin expression." (PMID 21415988, 2009).
neurodegenerative disease (8 papers, 2006 to 2024). A disorder of the central nervous system characterized by gradual and progressive loss of neural tissue and neurologic function. "HFE variants have been extensively investigated regarding their role in neurodegenerative disease due to the pathological effects of increased iron levels in the brain." (PMID 38542306, 2024). "Genetic variants of the HFE gene are unable to maintain iron homeostasis, and in particular, the H63D variant has been under investigation as a potential risk factor for neurodegenerative diseases." (PMID 25071582, 2014). "Polymorphisms in the MHC class 1-like gene known as HFE have been proposed as genetic modifiers of neurodegenerative diseases that include neuroinflammation as part of the disease process." (PMID 19228389, 2009). "In the current study we determine the influence of HFE variants and iron regulation on cellular secretion of factors relevant to neurodegenerative disease and explore mechanisms underlying these relationships." (PMID 19228389, 2009). "Carriers of HFE mutations have an increased risk of iron accumulation in the brain and show signs of oxidative damage, hence variants may contribute to the neurodegenerative disease process." (PMID 38542306, 2024). "The role of HFE variants in the pathology of neurodegenerative diseases remains highly debated." (PMID 38542306, 2024). "Thus, to understand and interpret the impact of HFE mutations on neurodegenerative disease, we strongly suggest that the data be viewed through the lens of the common process known as hormesis." (PMID 38542306, 2024). "It highlights the effects of gene variants of HFE (H63D- and C282Y-HFE) on iron and cholesterol metabolism and how they may contribute to understanding the etiology of complex neurodegenerative diseases." (PMID 25071582, 2014). "Because of mounting evidence that the presence of HFE mutations may increase risk or alter the course of many neurodegenerative diseases it became important to understand how the HFE protein is functioning to modulate iron transport at the brain but also other physiological barriers." (PMID 27457588, 2016). "HFE is an iron management protein that has received considerable interest over the last decade in neurodegenerative diseases." (PMID 27457588, 2016).
tumor (8 papers, 2013 to 2024). "We performed multiplex Cox regression to double check the bivariate associations (Kaplan-Meier curve) between HFE gene variant and overall survival by further controlling other possible factors (tumor stage etc.)that could contribute to the overall survival." (PMID 31856248, 2019). "Expression data from The Cancer Genome Atlas (TCGA) revealed a direct correlation between HFE and tumor grade, with the highest expression seen in GBM (grade IV)." (PMID 38239626, 2024). "To directly assess HFE function, we genetically manipulated Hfe levels in tumor cells to determine the effect on cell growth and survival." (PMID 38239626, 2024). "Taken together, it is convincing to believe that HFE down-regulation in liver grafts, as observed in this study, can lead to iron overload and eventually post-transplant tumor recurrence." (PMID 29642405, 2018). "There was an increased ratio at 5 SNVs (all intron positions of HFE gene) in tumor samples compared to the blood normal samples." (PMID 28358914, 2017). "One patient’s NB sample had C282Y heterozygote, but its tumor tissue had no mutation at 282 amino acid in the HFE gene." (PMID 28358914, 2017). "Stratification of the data by tumor site did not impact the association with the HFE C282Y and H63D genetic variants." (PMID 26690219, 2015). "Since iron is required for a number of cellular processes that are involved in tumour biology such as ROS generation, Wnt signalling and DNA synthesis, we reasoned that HFE knockdown would affect all these pathways, which was indeed the case, wherein siHFE significantly reduced ROS level." (PMID 23991213, 2013). "Next, we assessed the effects of HFE knock-down in an in vivo tumour model." (PMID 23991213, 2013). "While HFE expression has been reported to inform GBM survival, HFE function in tumor cells remains unclear." (PMID 38239626, 2024). "The downregulation of HFE may, in turn, promote MHC I presentation of tumor antigens which are recognized by antigen‐specific cytotoxic CD8+ T cells leading to tumor lysis and eradication." (PMID 28474781, 2017). "Overexpression of HFE in HNSCC leads to increased hepcidin, which in turn promotes intracellular iron accumulation, resulting in increased DNA synthesis, elevated ROS levels, Wnt signalling, all driving tumour cell proliferation and clonogenicity, with iron as a critical mediator in this process." (PMID 23991213, 2013).
infection (7 papers, 2012 to 2019). The state of being infected such as from the introduction of a foreign agent such as serum, vaccine, antigenic substance or organism. "Interestingly, HFE knock-out as well as β2M knock-out mice showed an increased susceptibility to experimental infection with M. avium and during infection these animals were found to accumulate iron inside the granuloma macrophages." (PMID 25356553, 2014).
bacterial infection (2 papers, 2017 to 2024). "The majority of these results suggest that both HFE and Hepcidin (encoded by the HFE and HAMP genes, respectively) play a protective role against bacterial infection in human and mouse." (PMID 28815056, 2017).
infectious disease (2 papers, 2011 to 2021). A disorder directly resulting from the presence and activity of a microbial, viral, or parasitic agent in humans. "This advantage against some infectious diseases may explain the high frequency of HFE mutations in the Caucasian population." (PMID 34766580, 2021).
movement disorder (1 paper, 2025). Neurological conditions resulting in abnormal voluntary or involuntary movement, which may impact the speed, fluency, quality and ease of movement. "Future studies should investigate the relationship between specific HFE gene variants and the phenotype of movement disorders." (PMID 40941762, 2025).
HFE also shares sentences with these, for which no sentence is quoted: metabolic disorder (6 papers); glioma (4); hyperferritinemia (3); metabolic dysfunction-associated steatotic liver disease (3); stomach cancer (3); cardiac diseases (2); chronic hepatitis (2); colorectal cancer (2); hemochromatosis type 2B (2); Hepatic fibrosis (2); Hypercholesterolemia (2); hypoparathyroidism (2); hypopituitarism (2); hypothyroidism (2); meconium ileus (2); metabolic syndrome (2); osteoarthritis (2); pericarditis (2); rheumatoid arthritis (2); Salmonella Infections (2); steatosis (2); thalassemia intermedia (2); acute leukemia (1); acute myeloid leukemia (1); adenocarcinoma of the lung (1); Adrenal insufficiency (1); alcohol use disorder (1); alcoholism (1); all (1); alpha 1-antitrypsin deficiency (1).
A further 61 diseases each share a sentence with HFE in 1 paper.